TNF (tumor necrosis factor)
Diseases named in the same sentence as TNF in open-access papers (continued):
Sharing a sentence is not in itself a finding about the gene and the disease.
Insulin resistance (continued). "It has been hypothesized that peripheral insulin resistance is augmented by stimulation of intestinal Toll-like receptor 4 (TLR4) primarily by LPS from Gram-negative Proteobacteria leading to secretion of proinflammatory cytokines such as tumor necrosis factor alpha (TNFα)." (PMID 24369539, 2013). "Bariatric surgery has been shown to ameliorate insulin resistance, improve the adiponectin level, and decrease IL-18, CRP, and TNF-α." (PMID 23431426, 2013). "In fact, inflammatory cytokines (for example, TNF-alpha) and Toll-like receptor 4 (TLR4), an obligatory receptor for bacterial LPS, are important participants in insulin resistance in critical illness." (PMID 23375099, 2013). "Interestingly, the proposed mechanism involved in sarcopenic obesity could be the increased production from adipose tissue of different substances, such as tumor necrosis factor-α (TNF-α) and leptin, which are known to influence insulin resistance and growth hormone (GH) secretion." (PMID 23690769, 2013). "A signaling cascade arising from TNF-alpha is shown in the KEGG pathway, resulting in increased insulin resistance." (PMID 26029481, 2013). "To evaluate the effect of EE on impaired glucose uptake in an insulin-resistant state, we induced insulin resistance using TNF-α treatment in 3T3-L1 adipocytes and measured the effect of EE on TNF-α-mediated suppression of glucose uptake." (PMID 23690865, 2013). "The downregulation of src kinase FYN seems to be a counteracting compensatory mechanism as this protein is important in IFN gamma action, in TNF alpha induced COX2 expression and in adipose tissue - mediated inflammation leading to insulin resistance." (PMID 24303025, 2013). "The adipokines adiponectin and tumor necrosis factor alpha (TNF-α) play a role in body fat distribution and correlate with aging and insulin resistance." (PMID 24455726, 2013). "In this review, mechanisms involving free fatty acids, adipocytokines such as TNFα and PPARγ and serine kinases like JNK and IKKβ, asserted to be responsible in the development of insulin resistance, will be discussed." (PMID 24324517, 2013). "TNF-α induces insulin resistance in BAT and directly inhibits BAT energy expenditure, aggravating insulin resistance." (PMID 24236066, 2013). "Although TNF-α levels in the circulation is positively correlated with insulin resistance, and neutralization of TNF-α improved the insulin sensitivity in rodents, clinical effects of TNF-α neutralization in humans are still controversial." (PMID 23781214, 2013). "ERK1 is an important mediator of inflammation-induced insulin resistance, insulin receptor substrate (IRS)-1 serine (inhibitory) phosphorylation, and the inhibitory effect of TNFα on insulin signaling." (PMID 23431246, 2013). "Adipokines like tumor necrosis factor-α (TNF-α) and interleukine-6 are largely produced by abdominal fat and have been related to insulin resistance." (PMID 23919592, 2013). "Studies on adipocytes and myocytes have suggested that TNFα will increase IRS-1Ser307 phosphorylation in high-glucose or diabetic conditions, contributing to insulin resistance." (PMID 23592917, 2013). "Moreover, TNF-alpha also has a role in the development of insulin resistance; in fact, it affects insulin sensitivity by changing the phosphorylation of insulin receptor substrate-1 and interferes with the insulin signaling cascade, thereby leading to insulin resistance." (PMID 24259948, 2013). "It has been reported that TNF-α secretions are elevated by the accumulation of fat in adipocytes and that TNF-α induces insulin resistance in obese animal models." (PMID 23365609, 2013). "This occurs by abolishing the stimulatory effect of TNFα on JNK1/2 kinase, which is directly involved in the development of insulin resistance." (PMID 24416031, 2013). "TNF-α is a typical pro-inflammatory cytokine that is increased in obese humans and rodents suggesting that TNF-α contributes to insulin resistance." (PMID 23781214, 2013).
Insulin resistance (continued). "In WAT of KK-Ay mice fed fucoxanthin, mRNA expression levels of pro-inflammatory adipocytokines, such as interleukin-6 (IL-6) and tumor necrosis factor-α (TNF-α), which are thought to induce insulin resistance, were markedly suppressed." (PMID 23820585, 2013). "Tumor necrosis factor-alpha (TNF-α) stimulation was also suggested to disrupt insulin signal transduction and induce insulin resistance." (PMID 23213270, 2012). "In visceral obesity, adipocytokines such as TNFα, resistin, IL-6 and FFA are secreted by enlarged fat cells of the internal organs as adipose tissue and induce insulin resistance." (PMID 22348333, 2012). "TNF-α stimulates the expression of key components of its own signaling pathway, notably Map4k4, through a TNFR1-dependent mechanism to induce insulin resistance in adipose tissue." (PMID 22816003, 2012). "We demonstrated that there is a correlation between the expressions of TNF-α in retroperitoneal WAT and insulin-resistance in 8 genetically obese fa/fa rats." (PMID 23056223, 2012). "It has been reported that the elevated inflammatory cytokines, especially TNF-α in the liver and serum in chronic hepatitis C, suggesting a possible link between HCV infection, inflammatory cytokines, and insulin resistance." (PMID 22675572, 2012). "TNF induces phosphorylation of IRS-1 at serine instead of tyrosine residues and promotes insulin resistance." (PMID 22691241, 2012). "Moreover, insulin resistance and increased adipose mass create an oxidative environment in the tissues that upregulates the expression of various pro-inflammatory cytokines, including tumor necrosis factor-α (TNF-α) and interleukin-6 (IL-6), which stimulate tumor growth and progression." (PMID 22312273, 2012). "Patients with high baseline insulin resistance demonstrated significant improvement in DAS28 (P = 0.013), HAQ (P = 0.012), and CRP (P = 0.007) after 12 weeks of treatment with anti-TNF agents." (PMID 22691241, 2012). "TNFα and IL-6 have been shown to inhibit insulin signaling through inhibitory phosphorylation of IRS1; ablation of these cytokines prevents insulin resistance in cells and in vivo." (PMID 24764512, 2012). "Several studies have shown that macrophage-derived cytokines and chemokines such as TNFα and MCP-1 can directly elicit adipose cell inflammation and insulin resistance." (PMID 22046423, 2011). "These M1 macrophages produce pro-inflammatory cytokines, such as tumor necrosis factor alpha (TNF-α), thereby contributing to a local and systemic chronic inflammatory status and insulin resistance." (PMID 22018099, 2011). "Out of the insulin-resistance mediating factors, plasminogen activator inhibitor-1 (PAI-1), MCP-1, IL-6, IL-8, IL-10 and tumour necrosis factor (TNF)-α were significantly elevated in these patients." (PMID 21470423, 2011). "Adipokines, such as tumor necrosis factor-α (TNF-α), interleukin-6 (IL-6), and adiponectin secreted from adipocytes and immune cells are predictors of vascular disease and insulin resistance." (PMID 20490354, 2010). "The use of TZDs in the treatment of T2D improves insulin resistance by increasing GLUT-4 levels and decreasing the levels of cytokines that induce insulin resistance, such as TNF-α and IL-6 by antagonizing the activity of proinflammatory transcription factors." (PMID 19746174, 2010). "TNFα and NF-κB suppress TSC1 inhibition of mTORC1, resulting in hyperactive mTORC1 activity, which contributes to insulin resistance." (PMID 20625397, 2010). "TNF-α and JNK are potential mediators of insulin resistance and are significantly upregulated in high-salt-fed-Dahl S rats." (PMID 18570670, 2008). "TNF-α induces insulin resistance through direct negative interference with the insulin signaling pathway, IRS1 phosphorylation, and alteration of adipocyte differentiation and metabolism." (PMID 41226064, 2025).
Insulin resistance (continued). "Compared to hs-CRP and TNF-α, which are elevated in PCOS and indicate a pro-inflammatory state, adiponectin functions as an anti-inflammatory regulator, where it counteracts insulin resistance and systemic inflammation effects by enhancing insulin sensitivity and reducing inflammation." (PMID 40385768, 2025). "In experimental animals, adipokines such as TNF-α, IL-6, Retinal binding protein-4 (RBP4), IL-18, lipocalin 2, as well as BCAA levels are linked to insulin resistance, although there is little evidence in humans." (PMID 39791169, 2025). "Visceral fat secretes pro-inflammatory cytokines (IL-6, TNF-α), promoting systemic inflammation and insulin resistance, which can lower HDL and raise non-HDL cholesterol, increasing cardiovascular risk." (PMID 40632711, 2025). "Inflammation-wise, the majority of the studies emphasized the ability of anthocyanins to reduce pro-inflammatory cytokines such as IFN-γ, IL-6, TNF-α, and MCP-1 that have a tendency to be elevated in obesity and contribute to insulin resistance and metabolic abnormalities." (PMID 40218884, 2025). "Furthermore, TNF inhibitors reduce the effects of TNF on CVD, such as dyslipidemia, insulin resistance, and adhesion molecules, which lead to inflammation and fatty streaks in the vascular walls." (PMID 39897309, 2025). "On one hand, periodontal disease triggers the release of inflammatory cytokines, such as interleukin-6 (IL-6) and tumor necrosis factor-alpha (TNF-α), which impair insulin signaling pathways, resulting in increased insulin resistance and poor glycemic control in diabetic patients." (PMID 40283848, 2025). "In periodontitis, TNF-α outnumbers the insulin molecule binding to the INS-R, thereby inhibiting insulin’s ability to activate the receptor and initiating glucose uptake, resulting in a state of insulin resistance." (PMID 40136728, 2025). "Research indicates that Pso has strong connections to metabolic syndrome and insulin resistance, while GLP-1RAs might provide anti-inflammatory benefits through the TNF-α and IL-17 pathways." (PMID 40422559, 2025). "MetS is characterized by caloric excess, insulin resistance, and dyslipidemia, which promote adipocyte hypertrophy, local hypoxia, and HIF-1α–driven low-grade inflammation with TNF-α, IL-6 and MCP-1 signaling, engaging NF-κB/JAK–STAT pathways and worsening insulin resistance." (PMID 41409612, 2025). "During WAT expansion, particularly in visceral depots, a pro-inflammatory state develops, characterized by increased local (intra-organ) and circulating levels of tumor necrosis factor alpha (TNF-α) and interleukins 1 (IL-1) and 6 (IL-6), which are major contributors to insulin resistance (IR)." (PMID 41283478, 2025). "Clinical studies further confirm that quercetin supplementation (≥500 mg/day for ≥8 weeks) in humans significantly improves FBG, Homeostatic Model Assessment of Insulin Resistance (HOMA-IR), and levels of the inflammatory markers (e.g., TNF-α and IL-6) in patients with T2DM and metabolic syndrome." (PMID 40864768, 2025). "Of note, it was shown that, in high-fat-diet (HFD)-induced obese rats, the combination of the drug Orlistat and the flavonoid hesperidin decreased body weight, blood glucose levels, the Homeostatic Model Assessment of Insulin Resistance (HOMA-IR) index, and TNF-α levels." (PMID 41155431, 2025). "Specifically, adipose tissue, especially visceral fat, secretes pro-inflammatory cytokines like tumor necrosis factor-alpha (TNF-α) and interleukin-6 (IL-6), which contribute to insulin resistance and may facilitate tumorigenesis in colorectal tissues." (PMID 40686812, 2025). "TNF-α is the cytokine responsible for steatohepatitis progression, patients with steatohepatitis have higher TNF-α levels, which play an important role in hepatic fibrosis, insulin resistance and type 2 diabetes." (PMID 40607347, 2025).
Insulin resistance (continued). "Most studies reported statistically significant reductions in multiple key inflammatory mediators, particularly TNF-α, IL-6, IL-1β, and CRP, which are central to the pathophysiology of insulin resistance, adipose tissue dysfunction, and cardiovascular complications in metabolic syndrome." (PMID 40868165, 2025). "These cytokines and chemokines, including tumor necrosis factor-alpha (TNF-α), interleukin-6 (IL-6), and monocyte chemoattractant protein-1 (MCP-1), contribute to endothelial dysfunction, insulin resistance, and renal impairment, all of which disrupt electrolyte homeostasis." (PMID 40136609, 2025). "Excess TNF may hamper PPAR-based lipid oxidation, provoking hepatic fat accumulation and insulin resistance." (PMID 40869340, 2025). "Similarly, the TNF-α/JNK pathway is also activated in T2DM, contributing to peripheral insulin resistance, β-cell apoptosis, and increased oxidative stress." (PMID 39966707, 2025). "In contrast to TNF-α, plasma rather than adipose IL-6 demonstrated the strongest relationship with obesity and insulin resistance." (PMID 41155523, 2025). "Finally, sleep problems activate pro-inflammatory pathways, increasing circulating interleukin (IL)-6, tumor necrosis factor (TNF)-α, IL-1β and C-reactive protein, which exacerbate insulin resistance." (PMID 41087614, 2025). "Among the pro-inflammatory cytokines, TNF-α emerged as a central player in the inflammatory response in T2DM patients, consistent with its established role in promoting insulin resistance and contributing to diabetic complications such as nephropathy, neuropathy, and retinopathy." (PMID 41030441, 2025). "It is likewise known that DM could increase cytokines ́ levels like tumor necrosis factor-α (TNF-α), cyclooxygenase 2 (COX-2) and Prostaglandin E2 (PGE2) leading to systemic inflammation and subsequently insulin resistance and alterations of insulin signaling." (PMID 39820827, 2025). "Increased levels of tumor necrosis factor-alpha (TNF-α), interleukin-6 (IL-6), and C-reactive protein (CRP) contribute to insulin resistance, oxidative stress, and enhanced cellular proliferation, creating a microenvironment conducive to CRC development and progression." (PMID 40444236, 2025). "Fourth, although the relationship between FGF-23, insulin resistance, and inflammatory parameters, such as interleukin, vascular cell adhesion molecule, and tumor necrosis factor, is known, these markers have not been studied." (PMID 39879508, 2025). "This microenvironment promotes the secretion of cytokines, such as TNF-α and IL-6, which impair insulin signaling by inhibiting the IRS-1/PI3K/Akt pathway, contributing substantially to the systemic insulin resistance observed in the Ob-Veh and HE-Ob-Veh groups." (PMID 41471698, 2025). "Notably, the study revealed the costimulatory effects of TNF-α and IGF-1 on preeclampsia with increased insulin resistance." (PMID 41155321, 2025). "Chronic low-grade inflammation—driven by TNF-α and IL-6 from adipose tissue macrophages—activates stress kinases Jun N-terminal Kinase (JNK) and I-kappa-B Kinase (IKK), promoting IRS1 serine phosphorylation and exacerbating systemic insulin resistance." (PMID 40943638, 2025). "Consistent with LJ3402's suppression of circulating inflammatory cytokines (TNFα and IL‐1β), LJ3402 administration mitigated age‐related insulin resistance and impaired thermoregulation, as demonstrated by improved glucose and insulin tolerance and increased cold resistance." (PMID 41346200, 2025). "Our findings also showed that exposure to 4-HNE, a reactive aldehyde known to increase inflammation, oxidative stress, and insulin resistance in preadipocytes, increased TNF-α levels in non-targeted, but not in GATA-3 knockout, cells." (PMID 39851528, 2025). "Additionally, the expression of inflammatory cytokines like TNF-α, IL-1β, and interferon-γ (IFN-γ) decreases, ultimately leading to improved insulin resistance." (PMID 40559421, 2025).
Insulin resistance (continued). "Resistin influences the synthesis of critical pro-inflammatory cytokines, including TNFα, IL6, and IL12, by activating NF-κB pathways in macrophages, leading to significant disruptions in peripheral insulin signaling and the development of insulin resistance." (PMID 40699839, 2025). "Inflammatory cytokines, such as tumor necrosis factor-alpha (TNF-α), interleukin-6 (IL-6), IL-1β, IL-1, IL-17, and monocyte chemoattractant protein-1 (MCP-1), contribute to the advancement of NAFLD by fostering insulin resistance, hepatic inflammation, and fibrosis." (PMID 41257640, 2025). "In addition, plasma TNF-alpha, which showed significantly higher levels in type 2 diabetes mellitus (T2DM) mice and rats, plays a crucial role in inducing insulin resistance, a circumstance that is also known from T2DM patients." (PMID 39120321, 2024). "Insulin resistance and T2DM are correlated with sustained low-grade inflammation, and probiotics such as Lactobacillus casei have been demonstrated to lower inflammation indicators, including CRP and TNF-α." (PMID 38931292, 2024). "Furthermore, LrB can reduce inflammation and insulin resistance in individuals with PCOS by inhibiting NLRP3, Caspase-1, TNF-α, IL-6, IL-1β, and IL-18 and increasing the expressions of GPR120, LKB1, and AMPK." (PMID 39456928, 2024). "The development of insulin resistance is significantly impacted by inflammation, and in this study, BPA-induced insulin resistance correlates with increased TNF-α and IL6 production, suggesting a connection between inflammation, diabetes, and pancreatic islet dysfunction." (PMID 38580733, 2024). "Tumor necrosis factor-alpha (TNF-α) plays a significant role in the pathophysiology of both diabetes and oral health, contributing to insulin resistance, inflammation, and tissue destruction, thus linking diabetes to periodontal diseases and other oral health complications." (PMID 38644951, 2024). "TNF-α, IL-6, IL-1β, and HOMA-IR were significantly lower in the semaglutide-treated group, suggesting that semaglutide has a beneficial effect on muscle function by reducing the inflammatory response and insulin resistance." (PMID 39125786, 2024). "Decreased lipocalin levels and increased inflammatory factors such as tumor necrosis factor and interleukin 1β can inhibit SHBG production and SHBG may be an early marker of insulin resistance and disorders of glucose and lipid metabolism." (PMID 38988998, 2024). "Insulin-stimulated spheroids (WA-TNF-α + Insulin) showed significant difference in glucose uptake compared to non-treated spheroids (WA + Insulin), indicating that the TNF-α treatment effectively blocked glucose uptake and induced insulin resistance." (PMID 38820505, 2024). "TNF-α was overexpressed in white adipose tissue (WAT) in obese and insulin-resistant states; mice lacking the TNF-α ligand were relatively protected from obesity-induced insulin resistance." (PMID 39124622, 2024). "Additionally, we assessed the mRNA levels of pro‐inflammatory cytokines (iNOS, TNF‐α, IL‐1β, and MCP‐1) in the adipose tissue of mice, all of which are known to contribute to insulin resistance." (PMID 39554331, 2024). "Although our study provided novel insights into the effects of ferulic acid on improvement in inflammation and insulin resistance by regulating the JNK/ERK and NF-κB pathways in TNF-α-treated adipocytes, the results obtained should be evaluated in an animal model, and finally, in a clinical trial." (PMID 38257186, 2024). "By inhibiting pro-inflammatory cytokines such as interleukin-6 (IL-6) and tumor necrosis factor-alpha (TNF-α), SB could reduce chronic inflammation, a key factor in insulin resistance and atherosclerosis." (PMID 39590851, 2024). "In addition, smoking is associated with increased pro-inflammatory cytokines, such as tumor necrosis factor-alpha (TNF-α) and interleukin-6 (IL-6), which can further contribute to insulin resistance." (PMID 38894993, 2024).